CCR9 (C-C motif chemokine receptor 9)
Diseases named in the same sentence as CCR9 in open-access papers (continued):
Sharing a sentence is not in itself a finding about the gene and the disease.
tumor (continued). "Researchers have shown that CCR9 that has been activated by its specific ligand CCL25 can interact with many signaling pathways, especially those involved in tumor chemoresistance and metastasis." (PMID 26879872, 2016). "We confirmed that CCL25/CCR9 influences the interaction of P-gp and the cytoskeleton protein ERM to increase P-gp efflux, thus mediating T-ALL tumor chemoresistance." (PMID 26879872, 2016). "Previously, we have also shown that over-expressed CCR9 interacts with CCL25 to promote proliferation and suppress apoptosis of NSCLC cells in vitro, and knockdown of CCR9 compromises in vivo tumor growth in a nude mice model." (PMID 26168791, 2015). "Our results demonstrate that the absence of CCR9 significantly increases the CD8+/Treg ratio in the tumor and peritumoral space, indicating that CCR9 plays a fundamental role in modulating the anti-tumoral immune response in CRC." (PMID 40305493, 2025). "CCR9, an upregulated gene in the list of DEGs, belongs to the G protein-coupled receptor family and is of great clinical relevance in T-ALL, particularly because of its relevance to tumor infiltration and metastasis." (PMID 37745085, 2023). "Using this cut-off, we could determine that from 495 tumor samples of T-ALL patients present in GENT2, >80% of them expressed high levels of CCR9 mRNA." (PMID 35967322, 2022). "The results indicated that PI3K/AKT was the main signal pathway activated by CCL25/CCR9 in SACC cells, which could enhance the proliferation and anti-apoptosis abilities of tumor cells." (PMID 36003306, 2022). "Since CCR9 can also be over-expressed in some non-hematopoietic tumors, the effect of 92R mAb on tumor burden was analyzed in HEK293T cells over-expressing a CCR9-GFP construct." (PMID 35967322, 2022). "CCR9/CCL25 can also activate Ras/Raf/MARK and RhoA/Rock signals to strengthen the degradation of ECM and change the cytoskeleton arrangement, thus enhancing tumor cell motility (Golec, Henao Caviedes & Baldwin, 2016)." (PMID 36003306, 2022). "Then, we used flow cytometry to label and analyze the number of CCR3+, CCR9+, CCR10+, CXCR2+, CXCR5+, and CXCR6+ cells expressed different isotype antibodies including IgA, IgG, and IgM in the lung metastases of cKO and control tumor-bearing mice." (PMID 33707428, 2021). "Unlike PD-L1 blockade, inhibition of CCR9 expression on tumor cells facilitates immunotherapeutic effects via tumor-specific T cells in vivo." (PMID 34545132, 2021). "In addition, there was positive correlation between the expression of CCR9 and ALDH1A1 in the same tumor microenvironment." (PMID 32308544, 2020). "Therefore, in this review, we focus on CCR9 as a potential tumor biomarker and on how the CCL25/CCR9 pathway is involved in tumor chemoresistance and metastasis." (PMID 26879872, 2016). "With the exception of some degree of reduced Lck phosphorylation (which was detectable only 5 min after exposure to CCR9lo tumor cells), we did not observe any CCR9-dependent changes in TCR signaling." (PMID 25691366, 2015). "To better understand the mode of CCR9-mediated immune suppression on T cells, we undertook broad-scale transcriptomics study to compare the changes in the transcriptome of T cells that encounter CCR9hi versus CCR9lo MCF7 tumor cells." (PMID 25691366, 2015). "Hence, higher expression of CCR9 in NSCLC suggests its potential role in dissemination of primary tumor and promoting tumor cell survival during metastasis." (PMID 25296976, 2014). "In this study, the results showed that CCL25/CCR9 could increase the expression of MMP2 and MMP9 by activating PI3K/AKT in SACC, which was confirmed in xenograft tumor mice, suggesting that CCL25/CCR9-activated PI3K/AKT might modulate MMPs through the transcription factor SLUG." (PMID 36003306, 2022).
tumor (continued). "The results showed that LY294002 could significantly inhibit the growth of SACC-LM cells induced by CCL25, but the number of dead tumor cells did not increase significantly when CCR9 inhibitor (VCN) was added into the tumor cells with the present of LY294002." (PMID 36003306, 2022). "Then, we focused on the tumor cell and lymphocyte interactions mediated by chemokines and demonstrated that mTEC-like and mcTEC-like tumor cells in TETs could induce DP cell migration for positive selection through CCL25:CCR9 and CXCL12:CXCR3 interactions." (PMID 36115836, 2022). "Furthermore, we found that after treatment with 92R mAb, the tumor cells present in the spleen and the liver did not have the CCR9 expression altered by the treatment." (PMID 35967322, 2022). "However, this immunotoxin did not eliminate all cancer cells, as some parts of the expanding tumor did not express CCR9, rendering CCL25-PE38 less than completely effective." (PMID 32957689, 2020). "This further supported the notion that CCR9-mediated immune suppression on T cells might be independent of its intracellular signaling in the tumor cells and rather affects the T cells directly." (PMID 25691366, 2015). "The difference in lysis between the different groups depended upon CCR9's expression on the tumor targets rather than on the T cell treatment (Fig6C), hinting to the possibility that T cells can interact directly with CCR9 on tumor cells." (PMID 25691366, 2015). "So far, an implication of CCR9 in T cell function or tumor-immune resistance has not been reported." (PMID 25691366, 2015). "In xenograft mouse models, we further proved that CCL25 could effectively promote tumor growth and suppress tumor apoptosis, and this enhancement could be reduced by inhibitors of CCR9 and PI3K/AKT, indicating that the PI3K/AKT signaling pathway played a key role in CCL25/CCR9 process." (PMID 36003306, 2022). "In addition, on non-hematopoietic tumors with forced CCR9 expression, 92R treatment had also an effect decreasing the number of subcutaneous tumor-carrying animals, as well as the tumor’s size, as demonstrated with HEK293T-CCR9 derived solid tumors as a proof-of-principle." (PMID 35967322, 2022). "Since the observed immune-modulatory effect was not based on CCR9-mediated tumor cell intrinsic signaling, nor mediated through soluble factors including CCL25, our data favor the assumption of a direct interaction between CCR9 on tumor cells and a yet unknown immune-modulatory ligand on T cells." (PMID 25691366, 2015). "In our study, the lack of CCR9−/− led to an increased CD8+/Treg cell ratio, indicating a stronger anti-tumoral immune response, which explains the reduced tumor number observed in these mice." (PMID 40305493, 2025). "We found that in the absence of CCR9, there is a significant increase of CD8+ T cells recruited to both the tumor and peri-tumoral zone zones and therefore, with a concomitant decrease in the frequencies of CD4+ T cells, as expected." (PMID 40305493, 2025). "Thus, the expression levels of CCR9 did not seem altered after treatment of the mice with 92R mAb and suggests that different strategies of administration or higher doses could be more efficient to reduce tumor burden." (PMID 35967322, 2022). "The expression of CCR9 and CALML3 mRNA was shown to be considerably reduced in tumor tissues when compared to non-tumor tissues as shown in To explore the prognostic importance of the hub genes we received overall survival plots (OS) using Kaplan–Meier method for each candidate hub genes." (PMID 40653567, 2025).
cancer (43 papers, 2010 to 2025). A tumor composed of atypical neoplastic, often pleomorphic cells that invade other tissues. "CCR9 associated with T lymphocyte development when bound to its specific ligand, and is highly expressed in variety of cancers." (PMID 31464612, 2019). "They include APOA1, VEGFC, YWHAZ, B2M, EIF2S1, CCR9 and many other genes that have been associated with the hallmarks of cancer." (PMID 25986937, 2015). "Mutations simultaneously occurring in LZTFL1 and CCR9 were the most frequent across cancers." (PMID 35141230, 2021). "CCR9 mediates immune cell homeostasis in the gut, and overexpression or aberrant expression is tied to several inflammatory disorders and cancer metastasis." (PMID 40154615, 2025). "They boost the host immunity during NSCLC immunotherapy by increasing Th1 lymphocytes and in IL‐12‐dependent manner, boosting the amount of IFN‐γ, and attracting CCR9 + CXCR3 + CD4 + T cells towards cancer cells." (PMID 38571678, 2024). "In recent years, CCR9 has been found in many cancers and proven to promote the malignant development of tumors once it interacts with its ligand CCL25." (PMID 36003306, 2022). "Some previous studies have shown that CCR9 is overexpressed in a variety of tumors and plays key roles in tumorigenesis and cancer progression." (PMID 34863167, 2021). "CCL25 is the specific ligand of CCR9, and both were highly expressed in various types of cancer and activate multiple signaling pathways, especially the pathways related to drug resistance as well as metastasis, thus related to poor prognosis." (PMID 33819196, 2021). "CCL25 fused to PE38 was constructed to target CCR9-bearing cancer cells including CCR9-high-expressing human T-ALL cells." (PMID 32957689, 2020). "Increased expression of CCR9 was detected on CSCs, which resulted in the migration and invasion of cancer stem cells through CCR9/CCL25 axis." (PMID 32308544, 2020). "Presently, others and we found that CCR9 is highly expressed in various cancers, and have focused on targeting therapy based on CCR9." (PMID 26879872, 2016). "Nevertheless, substantial work is still required, and future research efforts will provide us with a pharmacological basis of the therapeutic use of targeted therapy in cancer and a basis for the further investigation of other potential anti-CCR9 agents." (PMID 26879872, 2016). "CCR9 expression has been shown to be increased in various cancers, and CCR9 is specifically expressed in certain tissues." (PMID 26879872, 2016). "Further development of CCR9 as an immunotherapeutic target for cancer treatment would, however, require extensive toxicological analysis." (PMID 25691366, 2015). "The CC chemokine receptor 9 (CCR9) plays an important role in tumorigenesis and metastasis in various cancers." (PMID 26168791, 2015). "We exemplarily demonstrate that CCR9, which is expressed in many cancers, exerts strong immune-regulatory effects on T cell responses in multiple tumors." (PMID 25691366, 2015). "CCR9 is chemokine receptor involved in gut inflammation and cancer." (PMID 40825773, 2025). "CCR9 is responsible for migration and metastasis of many cancer cells." (PMID 40653567, 2025). "The results showed that the HIV peptides with the highest homology to TAAs identified in breast (CCR9), colon (EPCAM, GLOD5, CEACAM8) as well as prostate (NDUFS2) cancer and linked to most frequent HLA alleles (01:01; 02:01 and 24:02), are highly conserved across HIV isolates." (PMID 36243758, 2022). "Therefore, our findings suggest that CCR9 is a promising therapeutic target to inhibit the metastasis of OS and can serve as a novel prognostic marker, as it does in other cancers." (PMID 34863167, 2021). "However, this function of CCL25 results in intestinal metastasis of cancer cells with CCR9 expression." (PMID 33076281, 2020). "More and more studies have indicated that CCR9 could be viewed as an oncogenic biomarker in predicting metastasis and prognosis for cancer patients." (PMID 32308544, 2020).
cancer (continued). "CCR9 could enhance the proliferative and invasive ability of cancer stem cells and helped to recruit bone marrow-derived progenitors into the thymus." (PMID 31747966, 2019). "Anti-CCR9 mAbs have been used to demonstrate CCR9 mediation of antiapoptotic signals in cancer." (PMID 29670611, 2018). "This expression pattern suggests that CCR9 may participate in many important biological activities involved in cancer progression." (PMID 26879872, 2016). "Several studies have found that CCR9 is highly expressed in a variety of cancers." (PMID 26879872, 2016). "Therefore, CCR9 has become a potential targeted molecule for cancer therapy because it is highly expressed in various cancers." (PMID 26879872, 2016). "Notably, many different reports have shown that CCR9 is highly expressed in various cancer cells and tumors, functioning as a critical potential mediator in cancer progression." (PMID 26168791, 2015). "However, in colon cancer, CCR9 activation inhibits cancer cell migration." (PMID 33076281, 2020). "However, there were little studies concerning the effect of CCR9/CCL25 signal on cancer stem cells." (PMID 32308544, 2020). "Thus, a functional down-regulation of CCL25-mediated T lymphocyte recruitment in CRC tissue could potentially explain our results showing decreased numbers of CCR9+ T lymphocytes in carcinoma tissues compared to unaffected tissues." (PMID 29020986, 2017). "Missense mutations were noticed in all genes except CALML3 and IL1B.On the other hand methylation of hub genes were depicted in in which CCR9 and MUC5B were hypermethylated in CESC which can lead to gene silencing and promote metastasis of cancer." (PMID 40653567, 2025). "It acts as the ligand for CCR9, enhancing the CCR9/CCL25 signaling pathway, which has been shown to modulate cancer cell migration, invasion, and drug resistance." (PMID 38992592, 2024). "To preliminary clarify the underlying mechanisms, we investigate the correlation between CCR9 and ALDH1A1+cancer stem cells (CSCs), as well as the effect of CCR9 on the migration and invasion of CSCs." (PMID 32308544, 2020). "In cancer biology, activation of CCR9 by CCL25 promotes cancer cell migration, invasion and expression of matrix metalloproteinases (MMPs), which are key components of cancer invasion and metastasis." (PMID 26168791, 2015). "Many cancer cell types specifically express different CC and CXC chemokine-chemokine receptors, including CCR6, CCR9, CXCR4, and CXCR5." (PMID 25296976, 2014). "The current study shows OvCa tissue and cells significantly express CCR9, which interacts with CCL25 to support carcinoma cell migration and invasion." (PMID 20649989, 2010). "Furthermore, in most cancers, MHS were positively correlated with the expression of chemokine receptor genes such as CX3CR1 and CCR9 and negatively correlated with CXCR5 (P < 0.05)." (PMID 41174507, 2025). "In addition, CCR9 and CCL25 overexpression has been observed in malignant tumors and is correlated with metastasis to the colon." (PMID 40154615, 2025). "Considering the individual cancer-specific proteins, the highest number of HIV peptides homologous to TAAs (six) were predicted for the CCR9 (breast ca) and EPCAM (colon ca) proteins, covering the two most frequent HLA-A alleles in the world population (02:01 and 24:02)." (PMID 36243758, 2022). "We compared the expression of the 15 immune gene cancer tissues and adjacent tissues in the TCGA-BLCA cohort and found that the expression of the CCR9, IL7, PTGER4, IL10, CTSG, and ZBTB16 proteins in the adjacent tissues was significantly higher than that in the cancerous tissues (P < 0.05)." (PMID 32655621, 2020). "Moreover, the percentages of CCR9+CD8+ and CCR9+CD4+ lymphocytes were lower in carcinoma tissue as compared to unaffected tissues." (PMID 29020986, 2017). "There have been few studies regarding possible non-chemoattractant functions of CCR9, mainly in cancer models." (PMID 26230654, 2015).
cancer (continued). "To determine whether CCR9 is involved in the recruitment of CD4+ and CD8+ effector T cells during CRC development, we analyzed the cLP infiltrate under basal (CTRL), inflammatory (DSS) and cancer promoting conditions (AOM/DSS), using flow cytometry." (PMID 40305493, 2025). "Furthermore, the analysis of survival data on a limited amount of cancer patients showed a negative correlation between CCR9 expression levels and survival." (PMID 35967322, 2022). "However, it can be said that it cannot completely eliminate the established cancer, as some parts of the expanding tumors do not express CCR9, thereby rendering CCL25-PE38 ineffective." (PMID 26879872, 2016).